NEDD4 (NEDD4 E3 ubiquitin protein ligase)
Diseases named in the same sentence as NEDD4 in open-access papers (continued):
Sharing a sentence is not in itself a finding about the gene and the disease.
colon cancer (7 papers, 2014 to 2023). "Since NEDD4 is frequently overexpressed in cancers, including prostate, bladder, and colon cancers, NEDD4 was originally thought to be an oncogene." (PMID 38100351, 2023). "Another study in colon cancer tissues demonstrated that NEDD4 promotes the progression of cancer by activating FOXA1 ubiquitination in conjunction with the inhibition of miRNA-340-5p and the overexpression of ATF1." (PMID 36293239, 2022). "For example, in an in vivo study, it was reported that overexpression of NEDD4 enhanced the growth and metastasis of xenograft tumors, where it was abundantly expressed in colon cancer tissues and cells." (PMID 36293239, 2022). "A recent study showed that overexpression of FOXA1 reduces the proliferation induced by NEDD4 upregulation and promotes apoptosis in Caco-2/LoVo colon cancer cells." (PMID 36293239, 2022). "To clarify the role of Nedd4 and Nedd4l in intestinal tumorigenesis, we further crossed the mutant mice to Apcmin animals, a mouse model of colon cancer, to obtain Apcmin Nedd4 cKO, Apcmin Nedd4l cKO, and the compound Apcmin DKO mice." (PMID 31867777, 2020). "However, a couple of studies demonstrated the tumor-suppressive role of NEDD4 in colon cancer." (PMID 36293239, 2022). "For example, a study demonstrated that siRNA reduction of NEDD4 resulted in a decrease in cell proliferation and changed cell shape in LoVo and HCT-15 colon cancer cells." (PMID 36293239, 2022). "Another study on HCT-15 and LoVo colon cancer cells observed that PTEN and PI3K/Akt signaling are not required for NEDD4 to induce colon cancer cell growth." (PMID 36293239, 2022). "Furthermore, consistent with a possible oncogenic role for NEDD4, overexpression of NEDD4 was observed in human cancers such as prostate, bladder, colorectal and non-small-cell lung carcinomas (NSCLC) and promoted growth of colon cancer cells." (PMID 24657926, 2014).
neuroblastoma (7 papers, 2017 to 2023). Neuroblastoma (NB) is the most common solid, extracranial childhood tumor. "Exosomal hsa-miR 199-3p has the ability to enhance the proliferative nature of cancer by downregulating the NEDD4 level in neuroblastoma, indicating that exosomal hsa-miR199a-3p might be associated in the future development of novel therapeutic strategies for neuroblastoma." (PMID 36338993, 2022). "In contrast, the E3 ubiquitin ligase Nedd4 promotes JEV replication by suppressing autophagy in human neuroblastoma cells." (PMID 36988464, 2023). "A study on neuroblastoma revealed that exosomal hsa-miR199a-3p overexpression in NB can increase proliferation and migration in vitro by inhibiting NEDD4 expression, resulting in a poor prognosis." (PMID 36293239, 2022). "In this study, JEV infection induced elevated expression of Nedd4 in human SK-N-SH neuroblastoma cells." (PMID 28349961, 2017). "In SK-N-SH neuroblastoma cells, Nedd4 was up-regulated in response to JEV infection." (PMID 28349961, 2017).
nasopharyngeal carcinoma (6 papers, 2020 to 2025). A carcinoma arising from the nasopharyngeal epithelium. "In CNE1 and CNE2 nasopharyngeal carcinoma cells, it was found that partial overexpression of the NEDD4 signaling pathway caused EMT in DDP-resistant cells." (PMID 36293239, 2022). "One study found that cisplatin-resistant nasopharyngeal cancer cells overexpress the gene for NEDD4." (PMID 37605223, 2023). "NEDD4 has been associated with the progression and development of nasopharyngeal carcinoma (NPC)." (PMID 36293239, 2022). "Paeoniflorin downregulated the expression of NEDD4 and led to antitumor effects on nasopharyngeal carcinoma cells." (PMID 33288736, 2020). "Similarly, NEDD4 has been shown to contribute to epithelial–mesenchymal transition and cisplatin resistance in nasopharyngeal carcinoma cells." (PMID 38097550, 2023). "In addition, NEDD4 has also been implicated in chemoresistance in nasopharyngeal carcinoma (NPC)." (PMID 38097550, 2023). "Furthermore, NEDD4 knockdown improved cisplatin sensitivity in nasopharyngeal cancer cells that were resistant to the drug, showing that NEDD4 affects the level of sensitivity of cancer cells to it." (PMID 37605223, 2023). "A decrease in EMT in cisplatin-resistant nasopharyngeal carcinoma (NPC) cells was observed after upregulation of NEDD4 in cells, suggesting that NEDD4 could be a novel therapeutic target for overcoming drug resistance in NPC." (PMID 33935743, 2021).
viral infection (6 papers, 2015 to 2023). "Negative regulator like NEDD4 specifically promotes the degradation of activated phospho-TBK1 (p-TBK1) after viral infection." (PMID 37352355, 2023). "Recently, NEDD4 has been shown to have positive effects on several viral infections, including SARS-CoV-2 and the Ebola virus." (PMID 36498930, 2022). "It was first identified that NEDD4 directly targets TBK1 to induce K27-linked polyubiquitylation at K344 for degradation via the ALP, leading to the downregulation of type I IFN signaling in the late stages of virus infection." (PMID 36498930, 2022). "In addition, following viral infection, neural precursor cell expressed developmentally downregulated protein 4 (NEDD4) is ISGylated and blocks the interaction with the ubiquitin-conjugating enzyme (E2), further inhibiting NEDD4-induced ubiquitination to promote anti-viral immune response." (PMID 35149670, 2022). "Higher activity of NEDD4 and MLCP-CSKN2A as well as their regulating genes were observed after viral infection which increased the membrane fluidity and allowed the transmission of the virus to the tight junction of cells." (PMID 35774818, 2022). "On the other hand, neuron- and skeletal muscle-specific NEDD4 KO mice are viable, and NEDD4 is naturally inhibited by ISG15 during virus infections, perhaps suggesting that short-term inhibition of NEDD4 can occur without adverse effects." (PMID 26263374, 2015). "Therefore, we have identified NEDD4 as a regulator of IFITM3 levels and as a novel drug target for preventing influenza virus and other IFITM3-sensitive virus infections." (PMID 26263374, 2015). "Moreover, down-regulation of Nedd4 resulted in a significant decrease in JEV replication without alterations in virus attachment and internalization or in JEV pseudotyped virus infection, suggesting that Nedd4 participates in the replication but not in the entry stage of JEV infection." (PMID 28349961, 2017). "Unlike NEDD4, NEDD4L is an important E3 switch that actively induces the production of type I IFN and proinflammatory cytokines following virus infection." (PMID 36498930, 2022).
α-synucleinopathy (6 papers, 2014 to 2023). "Defective Rsp5/NEDD4 pathways were linked to α-synucleinopathy, which was supported by genetic screening in yeast." (PMID 26503960, 2016). "Manipulation of the activity of the ubiquitin ligase, Nedd4, promoted α-syn degradation with an associated reduction of dopaminergic degeneration, underscoring the connection between α-syn degradation and synucleinopathy." (PMID 37446200, 2023). "Altogether, APP, CLU, CALCA, and SOD1 may contribute to the α-synuclein-associated synucleinopathy, whereas NEDD4 by posttranslational modification protects against the formation of toxic α-synuclein inclusions." (PMID 36523604, 2022). "In yeast models of α-synucleinopathy Nedd4 constitutes an important node, whose manipulation modifies toxicity of α-synuclein through alteration of membrane trafficking, and Nedd4 over-expression has proven beneficial in small organism and mouse models of PD." (PMID 28124989, 2017). "Here we have provided compelling and novel in vitro and in vivo evidence that proteotoxic stresses, as exemplified by α-synucleinopathy, induce rapid and sustained HSF1 protein degradation mediated by the E3 ligase NEDD4 through UPS." (PMID 26503960, 2016). "Since reciprocal expression levels of NEDD4 and HSF1 were found in mouse and human tissue of α-synucleinopathy, we then sought in vivo evidence of α-syn-induced HSF1 degradation." (PMID 26503960, 2016). "In Drosophila and rat models of α-synucleinopathy, Nedd4 overexpression prevents neuronal dysfunction and pathology, and NAB2, an activator of the Nedd4 pathway, rescues α-synuclein toxicity in vitro in both yeast and human neuron α-synucleinopathy models." (PMID 31331333, 2019).
COVID-19 (5 papers, 2021 to 2024). A disease caused by infection with severe acute respiratory syndrome coronavirus 2. "Rare germline variants of WWP1 and NEDD4 can promote viral egress and are associated with severe COVID-19 cases." (PMID 38129384, 2023). "Notably, the two NEDD4 variants derived from COVID-19 patients were able to more avidly bind with the SARS-CoV-2 Spike (S) protein compared to wt-NEDD4." (PMID 33762578, 2021). "Expression analysis has revealed that WWP1 and NEDD4 are overexpressed in COVID-19-infected patients." (PMID 38129384, 2023). "Importantly, rare germline activating variants in the NEDD4 and WWP1 genes (HECT E3 ligase family members) are associated with severe COVID-19 cases." (PMID 38709105, 2024). "Moreover, they found that several rare variants in the NEDD4 E3 ubiquitin-protein ligase (NEDD4) and WW domain containing E3 ubiquitin-protein ligase 1 (WWP1) genes are associated with severe cases of COVID-19, when compared to asymptomatic controls." (PMID 37259386, 2023). "Moreover, we found that several rare variants in the NEDD4 E3 ubiquitin protein ligase (NEDD4) and WW domain containing E3 ubiquitin protein ligase 1 (WWP1) genes are associated with severe cases of COVID-19, when compared to asymptomatic controls." (PMID 36522315, 2022). "We next hypothesized that if HECT-E3 ligases are indeed functionally relevant for the viral life cycle of COVID-19, Indole-3-carbinol (I3C), a natural NEDD4 and WWP1 inhibitor from Brassicaceae, might display a direct antiviral effect." (PMID 33762578, 2021). "Importantly, rare germline activating variants in the NEDD4 and WWP1 genes are associated with severe COVID-19 cases." (PMID 33762578, 2021). "Interestingly, however, in PCR positive COVID-19 human lungs, NEDD4 and WWP1 were downregulated everywhere except in regions that expressed SARS-CoV-2 proteins." (PMID 33762578, 2021). "We then studied the expression of NEDD4 and WWP1 at protein level taking advantage of a COVID-19 mouse model and of available human lung specimens from infected patients necropsy." (PMID 33762578, 2021). "In PCR negative COVID-19 human lungs, the basal expression of NEDD4 and WWP1 was high." (PMID 33762578, 2021). "We finally evaluated whether selective inhibition of HECT proteins by a natural NEDD4 and WWP1 inhibitor from Brassicaceae displayed anti-SARS-CoV-2 activity, thus providing preclinical support for the possible development of clinical trials using this natural inhibitor in COVID-19 patients." (PMID 33762578, 2021). "We found that WWP1, WWP2, SMURF1, and NEDD4 mRNA are overexpressed in COVID-19 vs. SARS-CoV-2 negative patients in nasopharyngeal and oropharyngeal swab cells, as well as in the lung of affected patients and in mouse models of COVID-19." (PMID 33762578, 2021). "NEDD4 (FC = + 2.06, p ≤ 0.005), WWP1 (FC = + 1.85, p ≤ 0.0005), WWP2 (FC = + 4.11; p < 0.005) and SMURF1 (FC = + 1.7, p ≤ 0.05) showed a significant overexpression in nasopharyngeal and oropharyngeal swabs of COVID-19 positive patients compared to negative patients." (PMID 33762578, 2021).
gastric cardia adenocarcinoma (5 papers, 2019 to 2024). A carcinoma that arises from glandular epithelial cells of the cardia of stomach. "We recently reported that the expression of NEDD4 in gastric cardia adenocarcinoma tissues was significantly higher than that in adjacent normal tissue and was tightly associated with the prognosis of patients and gastric cardia adenocarcinoma metastasis." (PMID 34833029, 2021). "In addition, aberrant NEDD4 expression has been implicated in pathogenesis and is associated with an adverse prognosis in gastric cardia adenocarcinoma tumors." (PMID 31856858, 2019).
glioblastoma (5 papers, 2021 to 2025). The most malignant astrocytic tumor (WHO grade IV). "Dysregulation of NEDD4 in glioblastoma cells regulated PTEN expression by promoting its ubiquitination and degradation." (PMID 35705830, 2022). "In temozolomide (TMZ)-resistant glioblastoma cells, NEDD4–1 contributes to redox imbalance by promoting PTEN degradation and activating the AKT/NRF2/HO-1 pathway, while I3C treatment suppresses tumorsphere formation, migration, and invasion in resistant cell lines." (PMID 40370434, 2025).
lung adenocarcinoma (5 papers, 2018 to 2025). A carcinoma that arises from the lung and is characterized by the presence of malignant glandular epithelial cells. "Similarly, NEDD4 has been implicated to induce chemosensitivity in lung adenocarcinoma cells through inhibition of PTEN." (PMID 38097550, 2023). "More importantly, NEDD4 and EGFR are always co-expressed in lung adenocarcinoma tumor tissue, suggesting that NEDD4 might be associated with EGFR in lung adenocarcinoma." (PMID 29455656, 2018). "The ubiquitin ligase neural precursor cell-expressed developmentally downregulated 4 (NEDD4) has been attributed to the regulation of invasion, migration, and most importantly resistance to chemotherapeutic drugs in lung adenocarcinoma cells." (PMID 38097550, 2023). "Immunohistochemical (IHC) staining of lung adenocarcinoma indicates that NEDD4 is co-expressed with EGFR." (PMID 29455656, 2018). "Co-expression of NEDD4 with EGFR or PTEN was determined by immunohistochemical (IHC) staining in 63 lung adenocarcinoma tissue samples." (PMID 29455656, 2018). "Upregulation of NEDD4 was correlated with poor prognosis in lung adenocarcinoma." (PMID 33288736, 2020). "Our study identified several genes that may be associated with the survival of lung adenocarcinoma, in particular two new genes (ASB16, NEDD4)) that provide evidence for the prognosis of lung adenocarcinoma, and further studies are needed to confirm our findings." (PMID 34007304, 2020). "Both NEDD4 and EGFR are overexpressed in 41 lung adenocarcinoma samples out of total 63 samples, both overexpression rate in lung adenocarcinoma tumors are 65%." (PMID 29455656, 2018).
pulmonary fibrosis (5 papers, 2020 to 2026). Chronic progressive interstitial lung disorder characterized by the replacement of the lung tissue by connective tissue, leading to progressive dyspnea, respiratory failure, or right heart failure. "We found that the onset and progression of pulmonary fibrosis was associated with elevated levels of active TGFβ in lungs of conditional Nedd4-2−/− mice." (PMID 32332792, 2020). "In our study, we found striking differences in the pattern and development of pulmonary fibrosis in conditional Nedd4-2−/− mice compared with other experimental models of IPF." (PMID 39437758, 2024). "The development of pulmonary fibrosis in conditional Nedd4-2−/− mice is characterized by a long subclinical period followed by rapid progression of severe IPF-like lung damages at higher ages, highly similar to the disease dynamics in IPF patients." (PMID 32332792, 2020). "Moreover, in fibroblasts and idiopathic pulmonary fibrosis models, YY1 is regulated post-translationally by the E3 ubiquitin ligase NEDD4, which ubiquitinates YY1, alters its protein stability, and thereby modulates TAB1-dependent profibrotic proliferation and extracellular matrix production." (PMID 41560817, 2026). "Therefore, we believe that the downregulation of NEDD4 may enhance TGF-β stimulation and EMT to promote pulmonary fibrosis." (PMID 38215148, 2024).
adenoma (3 papers, 2013 to 2024). A neoplasm arising from the epithelium. "Consistently, loss of Nedd4 and/or Nedd4l resulted in an increase in Lgr5‐expressing stem cells in the adenomas." (PMID 31867777, 2020). "Loss of Nedd4/Nedd4l further promotes intestinal tumour progression to high‐grade adenomas in Apcmin tumour model." (PMID 31867777, 2020). "In contrast to the previous study, our data show that deletion of Nedd4 and/or Nedd4l in the intestinal epithelium alone is sufficient to accelerate adenoma development in Apcmin animals." (PMID 31867777, 2020). "On the other hand, the Wnt target gene Sox9 expression was significantly upregulated in all mutant adenomas when compared to control (Fig EV3G–J and O), suggesting that Wnt signalling is upregulated upon Nedd4 and Nedd4l loss." (PMID 31867777, 2020). "NEDD4 (213012_at) trended upward at the adenoma stage, but was significantly elevated in Stage 1 CRC and remained significantly elevated during tumor progression." (PMID 24312311, 2013). "Interestingly, expression of Nedd4 was significantly upregulated in Apcmin adenoma, while Nedd4l expression was unchanged." (PMID 31867777, 2020). "Loss of Nedd4 and Nedd4l enhances ISC proliferation, increases sensitivity to RSPO stimulation and accelerates tumour development in Apcmin mice with increased numbers of high‐grade adenomas." (PMID 31867777, 2020). "Since deletion of Nedd4 and Nedd4l increases ISC numbers under homeostasis, we further examined the ISC marker Lgr5 expression in control and mutant adenomas." (PMID 31867777, 2020). "Notably, NEDD4 mRNA expression was recently shown to be upregulated in CRC, but this analysis did not consider the stage of CRC, or include adenomas." (PMID 24312311, 2013).
Alzheimer disease (3 papers, 2022 to 2025). A progressive, neurodegenerative disease characterized by loss of function and death of nerve cells in several areas of the brain leading to loss of cognitive function such as memory and language. "In Alzheimer’s patients, ABCB1 protein levels were reduced, while NEDD4-1 protein levels were increased, suggesting NEDD4-1 as a therapeutic target for the treatment of Alzheimer’s disease." (PMID 35328067, 2022). "A decrease in NEDD4 is responsible for increased RTP801 gene expression, which contributes to neuroinflammation, memory impairment, and mortality in Alzheimer’s disease (AD)." (PMID 40725128, 2025).
Atrophy (3 papers, 2017 to 2025). Any weakening or degeneration, especially through lack of use. "Notably, other analyses were rendered impractical due to the limited number of studies on additional E3 ligases that have also been associated with muscle atrophy, such as MuRF-2/3, Nedd4, and MUSA1." (PMID 40331994, 2025). "The ubiquitin ligase Nedd4 participates in denervation-induced muscle atrophy in mice, and a relationship between myotonic dystrophy type 2 and NEDD4 has also been reported in human." (PMID 32938372, 2020).
kidney damage (3 papers, 2020 to 2025). "Both polydipsia and polyuria in Nedd4-2Ksp1.3 mice were exacerbated by high Na+, reminiscent of nephrogenic diabetes insipidus, often associated with kidney damage and mutations in aquaporin water channels." (PMID 33854040, 2021). "We propose that the high levels of ENaC aid in the reabsorption of elevated Na+ which in turn exacerbates kidney damage in Nedd4-2Ksp1.3 mice." (PMID 31802037, 2020). "Areas of kidney damage were obvious in Nedd4-2Ksp1.3 kidneys on a standard Na+ diet at P40, however after a low Na+ diet no kidney damage was apparent." (PMID 31802037, 2020). "Hence, osmotic diuresis and subsequent volume and hemodynamic changes are likely to contribute to kidney damage in Nedd4-2Ksp1.3 mice." (PMID 33854040, 2021). "We next assessed whether low dietary Na+ was affecting ENaC levels in Nedd4-2Ksp1.3 mice at P40, when nephropathy becomes more advanced." (PMID 31802037, 2020).